Y_RNA (Y RNA )
Gene: Miscellaneous RNA gene on chromosome 7 (7,102,573 to 7,102,681, reverse strand). Ensembl gene ENSG00000201218.
Homologues: Orthologues: chimpanzee Y_RNA (100% identical), macaque Y_RNA (93% identical). Paralogues in human: RNY1 (87% identical), Y_RNA (85% identical), Y_RNA (84% identical), RNY1P11 (83% identical), Y_RNA (83% identical), RNY1P12 (82% identical), Y_RNA (82% identical), Y_RNA (81% identical), RNY1P7 (80% identical), Y_RNA (80% identical), RNY1P8 (79% identical), Y_RNA (79% identical), and 94 more.